IL4 (interleukin 4)
Diseases named in the same sentence as IL4 in open-access papers (continued):
Sharing a sentence is not in itself a finding about the gene and the disease.
prostate carcinoma (continued). "By contrast, the data support a direct role for IL-4 in the progression of prostate cancer from androgen responsive, to advanced castrate-resistant disease." (PMID 24213139, 2011). "IL-4, which is found in the stroma of tumour regions of the prostate, upregulates anti-apoptotic proteins in prostate cancer cells." (PMID 20808855, 2010). "Treatment of recurrent prostate cancer patients with 200 μmol/day of SFN-rich broccoli sprout extract for 20 weeks also caused a statistically significant decrease in plasma levels of IL-1β, IL-4, and IL-13." (PMID 41802185, 2026). "Also, expression of IL-4 in androgen-dependent prostate cancer cells can induce androgen-independent growth." (PMID 30158439, 2018). "A study on prostate cancer showed elevated IL-4 level in patients with hormone-refractory cancer." (PMID 28927416, 2017). "IL-4 may therefore contribute to disease relapse by providing a niche that is favourable for the clonogenic growth of prostate cancer stem cells." (PMID 28553931, 2017). "A previous study demonstrated that PC-3 prostate cancer cells and U937 promonocytic cells enhanced tumor growth and increased tumor angiogenesis; they determined that IL-4 was a crucial cytokine regulating the differentiation of monocytes and macrophages into TAMs in prostate cancer cells." (PMID 27073100, 2017). "In addition, IL-4 has been shown to increase the proliferation of colon, breast, head and neck, ovary, and prostate cancer cells in vitro." (PMID 27895317, 2016). "Together, our data are consistent with a dual role for IL-4 in prostate cancer development." (PMID 24213139, 2011). "We confirmed the presence of IL-4 IR in prostate cancer epithelial tissue, and found that incubation of both human androgen-insensitive PC-3 cells and rat Dunning R3327 AT-1 prostate cancer cells with IL-4 for 24 h produced a significant increase in FAAH activity of the cells." (PMID 20808855, 2010). "In summary, the present study suggests that cytokine gene polymorphisms, including IL-1β rs16944, IL-4 rs2070874, IL-4 rs2227284, IL-16 rs7175701, and IL-16 rs11556218 may not be risk factors for prostate cancer in a population in central China." (PMID 36034203, 2022). "In addition, IL-4 promotes the clonogenic expansion of prostate cancer stem-like cells." (PMID 30158439, 2018). "In prostate cancer and oral cell squamous carcinoma, iNKT cells exhibit defective IFN-γ production but acquire IL-4 production ability." (PMID 36830717, 2023). "Another study also reported the absence of correlations between pretreatment and post-treatment serum concentrations of IL-4, IL-6, IL-10, and TNF-α, and fatigue symptoms in a group of 29 prostate cancer patients treated with radiotherapy." (PMID 36368974, 2022). "Increased syncytin-1 and annexin-V expression levels concomitant with an enhanced fusion frequency were observed in IL-4- and IL-13-treated PC3 prostate cancer cells." (PMID 35562905, 2022). "Goldstein and coworkers, 2011, showed a different immunoreactivity of IL-4 in prostatic cells of BPH and prostatic cancer." (PMID 28386549, 2017). "Interleukin-4 (IL-4) receptor IR was found on tumour epithelial cells and incubation of prostate cancer PC-3 and R3327 AT1 cells with IL-4 increased their FAAH activity." (PMID 20808855, 2010). "The TH2 cytokine interleukin-4 (IL-4), which has been reported to regulate FAAH and CB1 receptors in lymphocytes and Jurkat cells, is involved the pathogenesis of several cancer types, including prostate cancer." (PMID 20808855, 2010). "To understand the role of prostate cancer exosomes in macrophage polarization, we first induced THP1 cells into macrophages with 10 ng/ml PMA for 72 h, and then these macrophages were treated with IFN-γ (50 ng/mL), IL-4 (25 ng/mL), 2B4-exos (100 μg/ml), and IE8-exos (100 μg/ml)." (PMID 35941539, 2022).
prostate carcinoma (continued). "Moreover, studies in patients with prostatic cancer have indicated that aspirin, a nonsteroidal anti-inflammatory drug used for prostatic inflammation, is able to increase the serum levels of IL-4." (PMID 28386549, 2017). "We therefore propose that although the interleukin-4/STAT6 axis does not appear to be involved in therapy resistance, it does play a crucial role in the colony-forming abilities of the basal cell population in prostate cancer." (PMID 28553931, 2017).
Hypertension (37 papers, 2013 to 2025). The presence of chronic increased pressure in the systemic arterial system. "IL-4 levels have been seen to be lower in hypertensive patients compared with control, and serum IL-4 and gene expression levels are reduced in patients with a particular cholesteryl ester transfer protein Taq1B polymorphism, and is associated with hypertension in this group." (PMID 30747398, 2019). "Hypertension progression was associated with VEGF-A, IL-6, IL-4, and MCP-3, while newly detected hypertension was linked to IL-9, TNFa, IL12(p40), IFNa2, and EGF." (PMID 37629267, 2023). "After adjusting expectoration, chest pain, low fever, COPD, IFN-γ, hypertension, hemoptysis, IL-4, IL-6, and IL-12, miR-378 was independently correlated with the activity of TB patients (P = 0.047, OR = 39.016, 95% CI: 1.054–1444.199)." (PMID 35305574, 2022). "Further, the changes in Th1/IFN-γ and Th2/IL-4 levels were related to Ang II-induced hypertension or the onset of kidney injury." (PMID 32148441, 2020). "There is also accumulating evidence on the role of cardiac mast cell-IL4 axis in the mediation and development of hypertension-related cardiac fibrosis." (PMID 28707261, 2017). "Additionally, LOS + EV abrogated systemic hypertension, proteinuria, and albuminuria, and stimulated local gene overexpression of the endogenous anti-inflammatory Il-4." (PMID 40136683, 2025). "Furthermore, IL-4 plays a detrimental pro-fibrotic role in hypertension-induced cardiac remodelling and dysfunction in mice." (PMID 37949903, 2023). "Thus, the aim of this work was to determine the Th1/Th17 (IL-6, IL-2, TNF, IL-17 and IFN-γ) and Th2 (IL-4 and IL-10) serum profile in Venezuelan Chagasic patients stratified according amiodarone treatment, hypertension and arrhythmias." (PMID 28327099, 2017). "Assuming that inflammation may be the underlying mechanism in the relationship between MASLD and hypertension, we evaluated cytokines (TNF-α, IL-6, IL-10, IL-4, and IL-13) in the liver of patients with morbid obesity, MASLD, and SAH compared to patients without SAH." (PMID 39337863, 2024). "Moreover, pregnant interleukin-4 (IL-4 -/-) exhibit mild preeclampsia-like symptoms, and interleukin-10 (IL-10 -/-) knockout mice exposed to hypoxia present placental injury, proteinuria, and hypertension." (PMID 35493783, 2022). "In addition, many studies suggest that changes in serum levels of IFN-γ, IL-4, and IL-17, which are the characteristic factor of Th1, Th2, and Th17, respectively, may play a role in hypertension." (PMID 28757677, 2017). "Expression of IL-10, IL-8, IL-1β, IL-6, IL-4, TGFβ1, TNFα and GM-CSF significantly decreased in the CSWT group compared with the hypertension group." (PMID 36362064, 2022). "The hypertension could alter the cytokine profile as we observed that these 9 patients differed from other MDs by CTACK, IP10, MIG, IFNγ, and IL4 levels." (PMID 36175465, 2022). "Magnesium acts as an allosteric activator for adenylate cyclase, Na/K-ATPase, and phospholipase C. Magnesium downregulates IL-1 alpha, IL-4, IL-6, IL-1 beta, Il-10, IL-12, TNF-alpha and several chemokines involved in hypertension, numerous immune-inflammatory pathways, and in adverse pregnancies." (PMID 38807919, 2022). "Within MD group, patients with hypertension had significantly higher levels of CTACK, IP10, MIG, IFNγ, and IL4 than these without hypertension (independent sample t-test)." (PMID 36175465, 2022). "Prior work in a model of rats that develop hypertension has shown that the infusion of Ang II increased the number of type 1 T helper (Th1) cytokine IFN-γ-secreting cells and decreased type 2 T helper (Th2) cytokine IL-4-secreting cells." (PMID 31360120, 2019). "In hypertension, in addition to the existing therapy, targeting the Ang II-Gal-3-IL6 axis or the mast cell-IL4 axis using Gal-3 inhibitors or IL4 inhibitors could specifically reduce cardiac fibrosis [63, 118••, 119]." (PMID 28707261, 2017).
Hypertension (continued). "IL-4 levels in the hypertension group, especially in nondipper patients, were markedly lower than those in the control group." (PMID 28757677, 2017). "We demonstrated that although fetal growth and development was not affected in IL-4−/− mice, mild PE-like symptoms such as hypertension and proteinuria developed during pregnancy." (PMID 24904596, 2014). "Importantly, non-pregnant IL-4−/− mice did not exhibit hypertension and proteinuria at baseline or following TLR3 activation." (PMID 24904596, 2014). "P-PIC TLR3 KO mice did not develop hypertension and placental HIF-1α, NF-κBp50, miR-210, STAT6, and IL-4 levels were unchanged." (PMID 23844087, 2013).
type 2 diabetes (37 papers, 2012 to 2026). "There was significant different frequency of IL-4 -590 genotypes and alleles between Iranian type 2 diabetic cases with nephropathy and healthy controls." (PMID 35366956, 2022). "Several pieces of evidence from previous studies revealed that IL-4 and IL-10 depletion is associated with pronounced ulcerative colitis and Crohn’s disease, type 2 diabetes, metabolic syndrome." (PMID 36569878, 2022). "An association has been described between the IL-4/IL-4R genotype and type 2 diabetes as well as between IL-4 genotypes and high-density lipoprotein cholesterol." (PMID 32585823, 2020). "Epidemiological and clinical studies have shown that coffee consumption may reduce the levels of pro-inflammatory biomarkers such as interleukin(IL)-1b, IL-4, IL-6, IL-10, and C-reactive proteins, which can contribute to a reduced risk of type 2 diabetes." (PMID 32722593, 2020). "For example, IL4 appeared to be protective against type 1 diabetes with ketoacidosis, diabetic polyneuropathy, and type 2 diabetes with neurological manifestations." (PMID 40906170, 2025). "This work thus demonstrates the benefit of engineered cytokine constructs, in particular IL-4, for inducing skin regeneration, using a model of type 2 diabetic wound healing as a proof-of-concept." (PMID 37696884, 2023). "Thiazolidinediones (TZDs), an FDA-approved class of PPAR agonists used to manage type 2 diabetes, improved the outcomes of anti-IL-4/IL-13 for treating AD in obese mice by reducing immunological misfiring." (PMID 36614274, 2023). "In this regard, the intravenous infusion of insulin leads to the suppression of IL-4 expression in mononuclear cells from obese patients with type 2 diabetes." (PMID 28696379, 2017). "We utilize this collagen-binding, serum albumin-fused IL-4 variant (CBD-SA-IL-4) delivered in a hyaluronic acid (HA)-based gel for localized application of IL-4 to dermal wounds in a type 2 diabetic mouse model known for poor healing as proof-of-concept for improved tissue repair." (PMID 37696884, 2023). "It has been reported that IL-4 is down-regulated in patients with type 2 diabetes." (PMID 26211001, 2015). "The top canonical pathways regulated in amygdala of conditioned versus control were growth hormone signaling, axon guidance signaling, Notch signaling, type II diabetes signaling, and other immune-related signaling pathways such as chemokine networks, NFκB signaling and IL-4 signaling." (PMID 26317099, 2013). "Wang’s animal study stands alone in demonstrating the increased expression of pro-inflammatory cytokines TNF-α, IL-6 and IL-1β and the decreased expression of anti-inflammatory cytokines IL-4 and IL-10 in the midbrain of MPTP-treated type 2 diabetic mice." (PMID 40672460, 2025). "IL-4, an anti-inflammatory cytokine, and TNF-α, a proinflammatory cytokine, levels shift in both type 1 and type 2 diabetes." (PMID 30345315, 2018). "Furthermore, another study found a significant link between increased AAR and the levels of inflammatory cytokines such as IL-4, IL-6, and TNF-α in type 2 diabetes." (PMID 40408358, 2025). "Two clinical studies reported increased serum levels of anti-inflammatory cytokines (IL-4 and IL-10) and decreased levels of TNF-α, IFNγ, IL-12, and IL-6 in females with type 2 diabetes who received 8 weeks of daily NUTRIOSE® supplementation (10 g/day) versus baseline levels." (PMID 37836513, 2023). "We show for the first time that Pio treatment significantly suppresses the systemic inflammatory status in the BBDZR/Wor type 2 diabetes rat model by the selective growth of newly differentiated CD3+ T cells and by increasing CD3+IL-4 production in immigrant spleen lymphocytes." (PMID 26336514, 2015).
fibrosis (36 papers, 2013 to 2026). the formation of excess fibrous connective tissue in an organ or tissue in a reparative or reactive process. "In IPF, the Th2-type immune response, characterized by the production of IL-4, is associated with the promotion of fibrosis." (PMID 40110130, 2025). "Knockout of proteins that promote an M2/IL-4-like activation phenotype has been reported to protect against bleomycin-induced fibrosis and reduce expression of markers associated with IL-4-induced activation of macrophages in the lung." (PMID 36309093, 2022). "In our study we found decrease of DC-SIGN expression on liver endothelial cells in patients with advanced fibrosis that is presumably associated with the decrease of IL-4 and IL-13 production." (PMID 31318916, 2019). "Based on the evidence that IL-4 could stimulate fibroblast collagen expression and was associated with fibrosis and the pre-existing inflammation in the skin of IL-4 Tg mice before disease onset, we hypothesized that skin injury might result in a hypertrophic scar or chronic wound." (PMID 26752054, 2016). "We then examined in vivo CD8 T cells in the liver of the TAA-induced fibrosis model treated with IL-34 + IL-4 Mf." (PMID 39856797, 2025). "Stimulation with the Th2 cytokines IL-4 and IL-13 significantly increases hCLCA1 protein expression in mucosal tissue explants from the upper airways of fibrosis patients." (PMID 33066398, 2020). "For the serum level of IL-4, it was significantly decreased in 4-week fibrosis mice but showed an up-trend in cirrhosis patients." (PMID 28465467, 2017). "They participated in autoimmune and tissue fibrosis by producing IL-4 and IL-13." (PMID 36408259, 2022). "IL-4 and IL-13 have a key role in the development of pneumonitis and fibrosis." (PMID 30607342, 2018). "It was also shown that overexpression of IL-10 aggravates silica-induced pulmonary inflammation and fibrosis in mice, which might relate to the promotion of Th2-type cytokine reaction and increased expression of IL-4 and IL-13." (PMID 29673394, 2018). "Under an interventional approach, LASSBio-448 reversed ongoing lung eosinophilic infiltration, mucus exacerbation, peribronchiolar fibrosis and AHR by allergen provocation, in a mechanism clearly associated with blockade of pro-inflammatory mediators such as IL-4, IL-5, IL-13 and eotaxin-2." (PMID 27695125, 2016). "Additionally, IL-4 and IL-13 participate in fibrosis of skin and internal organs." (PMID 36985596, 2023). "We first evaluated the frequency of T CD4+ lymphocytes expressing IL-4, IL-5, and IL-13 after stimulation with SEA, since these cytokines are the main molecules involved in the pathogenesis of periportal fibrosis related to Schistosoma mansoni infection." (PMID 33692784, 2021). "We did not observe a significant difference in correlation of the frequency of CD4+T cells expressing TGF-β with CD4+ IL-4+ and CD4+IL-13+ T cells in the group of individuals with periportal fibrosis." (PMID 33692784, 2021). "There was no impact of liver steatosis on IL-4, IL-5, IL-10 and IL-22 levels in patients with mild fibrosis." (PMID 39200991, 2024). "Compared with BA patients without fibrosis, plasma levels of 3 anti-inflammatory cytokines including IL-4 (P = 0.026), IL-10 (P = 0.048), and IL-13 (P<0.001) were significantly increased in those with fibrosis." (PMID 35452452, 2022). "IL-4 is a strong stimulator for collagen synthesis, especially collagen I and III in fibrosis." (PMID 26752054, 2016).